CD4 (CD4 molecule)
Diseases named in the same sentence as CD4 in open-access papers (continued):
Sharing a sentence is not in itself a finding about the gene and the disease.
infection (continued). "Upon infection with SARS-CoV-2, humans generate SARS-CoV-2-specific antibodies, memory B cells, and CD4+ and CD8+ T cells, which all have complementary functions in the clearance of SARS-CoV-2 virions and infected cells." (PMID 35185909, 2022). "Our results on the dynamics of CD4+ and CD8+ T cells after B. bovis infection differ from previous observations following infection with an in vitro culture attenuated B. bigemina strain." (PMID 36466866, 2022). "We recruited 71 PLWH with a mean (±SD) age of 62±2.4 years; CD4 count, 553±249 cells/μL; CD4:CD8 ratio, 1.03±0.58; duration of infection, 20.0±7.7 years under efficient treatment during at least two years (<50 copies/mL and less than 2 viremic blips)." (PMID 35916394, 2022). "The phenotypic characterization of single-epitope-specific CD4+ T cells in other hepatic viral infections, such as HBV and HCV, has elucidated the role of CD4+ T cells in infection control." (PMID 35215790, 2022). "Especially during the infection of virus, bacteria or parasites, TNF-α can activate CD4 T cells, enhance the kill capacity of macrophage, induce death of infected cells." (PMID 35491409, 2022). "Cross-reactive CD4 CTLs would release IFN-γ, TNF, and LT, inducing the expression of MHC class II molecules on β cells, allowing for the infection of β cells by EBV." (PMID 35894054, 2022). "As expected, flow cytometry showed a depletion of CD4+ T cells and expansion of CD8+ T cells during primary infection and early cART (Group 1) preserved CD4 T cells count during chronic phase." (PMID 35185880, 2022). "The depletion of both CD4+ and CD8+ T-cells in mice led to an inability to clear the virus during primary infection." (PMID 35563292, 2022). "In addition, the MR can serve as an entry receptor for Dengue virus and can also interact with HIV-1 virions that may facilitate trans-infection of CD4+ T lymphocytes like other cell surface molecules, including dendritic cell-specific ICAM-grabbing non-integrin (DC-SIGN) and the integrin α4β7." (PMID 35328442, 2022). "Close interaction of macrophages and DC with T lymphocytes CD4+ and CD8+ is required for the effective control of infection." (PMID 35163035, 2022). "In response to H. pylori SS1 infection, IFN-γ+ CD4 T cells increased in the spleens of immunized mice compared to the controls." (PMID 36466847, 2022). "These repertoires capture the influence of multiple selective pressures, including thymic lineage selection (CD4+/CD8+), peripheral differentiation (along the naive-memory-effector axis), migration (spleen – bone marrow), aging, and infection." (PMID 35967295, 2022). "Infections by SARS-CoV-2 are usually characterized by significant lymphopenia, with depletion of CD4+ and CD8+ T cells." (PMID 35632475, 2022). "Lungs of Vhl Hif1a dcKO and WT mice also showed similar frequencies of central and effector memory CD4 and CD8T cells at 4 and 7 weeks after infection." (PMID 36064840, 2022). "During initial infection, the host mounts an HIV-specific immune response with the development of HIV-specific CD4+ and CD8+ T cells." (PMID 35972938, 2022). "A previous study revealed that CD4+ MAIT cells also produce more IL-2 cytokine in comparison to other cytokine subsets, indicating their potential role in early infection and latency." (PMID 35056035, 2022). "In fact, most SARS-CoV-2–infected individuals continue to have circulating memory B cells, bone marrow plasma cells, T follicular helper cells, and CD4 and CD8 Th1 cells present for 8 to 11 months after infection." (PMID 35019861, 2022). "However, the authors did show that Mtb glycolipids might potentially impair or enhance HIV trans-infection (DC capture and presentation of viral antigen to CD4+ T cells) of both R5 and X4 tropic HIV strains, which has important implications for virus transmission and dissemination." (PMID 36405707, 2022).
infection (continued). "Additionally, the frequency of IL-10+ CD4+ T cells correlated with protection against symptomatic infection and induction of asymptomatic infection, consistent with the hypothesis that Tr1 cells can protect against excessive pathology during infection and may contribute to clinical immunity." (PMID 36389662, 2022). "Memory CD4+ T cells contributed to immunity following the secondary infection, and depletion of both CD4+ and CD8+ T-cell subsets enhanced the infection and decreased survivability." (PMID 36177012, 2022). "After the secondary infection, the innate immune system cells and cytotoxic T CD8+ lymphocytes, helper CD4+ lymphocytes, and CD54+ cells quickly reacted." (PMID 35625758, 2022). "A case study of a single child with rotavirus diarrhea showed a depressed CD4+ T-cell frequency and CD4+:CD8+ ratio in an acute phase that persisted up to one-month post-infection but normalized by convalescent period." (PMID 35336866, 2022). "PTGER2 was significantly upregulated in both CD4+ (p=0.0039) and CD8+ (p=0.0086) T cells in active infection, as were CD4+ TNF expression (p=0.0364) and CD4+ EGR2 expression (p=0.0069)." (PMID 36439147, 2022). "Upon exposure to the virus, CD4 T lymphocytes activate B lymphocytes and CD8 T lymphocytes and provide protection against infection." (PMID 36560556, 2022). "The T‐cell independence of this naive ABC response is consistent with the known reduction of naive CD4 T cell response, including TFH, to infection and to vaccines with age." (PMID 36056604, 2022). "IM immunization results in robust CD4 and CD8 T cell responses that play a critical role in controlling viral replication post infection." (PMID 35935987, 2022). "Cross-reactive T cell epitopes associated with CD8 and CD4 T cells have been localized to the non-structural proteins as well as the E protein and induce either cross-protection or immunopathology in homotypic as well as heterotypic infections involving JE serocomplex viruses." (PMID 36298768, 2022). "Expansion of CD4+ and CD8+ T cells in the DCLNs became more pronounced after progression to the chronic stage of infection, with the peak in number of activated CD4+ and CD8+ T cells occurring at 6–8 wpi." (PMID 36541708, 2022). "It has been shown that in a mouse model of infection with L. donovani, IFN-γ+ CD4+ T cells died by apoptosis via TLR7-mediated IRF-5 upregulation of DR5; the authors suggested that this was triggered by tissue disruption." (PMID 35106507, 2022). "The peak levels of SARS-CoV-2-specific memory CD4 and CD8 T cells was found to be in the first month of infection, and then slowly declined in the following 6~7 months." (PMID 35874952, 2022). "In contrast, by day 14 post infection, P25TCR-Tg CD4 T cells had proliferated and expanded in mediastinal lymph nodes of mice infected with strain 4334 but not H37Rv." (PMID 35695454, 2022). "Antibodies and cytokines produced by B lymphocytes and the activation of CD4+, CD8+, γδ+, and NK+ T lymphocytes are critical for infection control and progression to the chronic phase." (PMID 35154155, 2022). "Memory CD4+T and CD8+ T cell responses are present in over 90% of recovered individuals in the first month after infection and remain constant over the first 8 months." (PMID 35911696, 2022). "The current knowledge of T-cell metabolism in HIV infection indicates that the HIV virus exploits the glycolysis of CD4+ T cells to both infect and enhance replication rate, while high glycolytic rate of CD8+ T cells confer resistance to infection." (PMID 35359994, 2022). "Animals treated with deprenyl showed decreases in CD4+ T cells; however, CD8+ T cells showed little change with infection." (PMID 35494221, 2022). "Consequently, the induction of the CD3+CD4+ T immune response to IAV may reduce the course and infection of the clinical disease by maximizing the clearance of virus-infected cells in mice because the CD3+CD4+ T-cell response plays a basic role in the prevention of IAV infection." (PMID 35722312, 2022).
infection (continued). "Plasma immunoglobulin G (IgG) levels were quantified, lymphocyte phenotyping was performed, and SARS-CoV-2 specific CD4 and CD8 T cell responses after in vitro antigen stimulation were assessed at six months post infection." (PMID 35743605, 2022). "Compared to pre-infection levels, the percentage of lymphocytes expressing the early activation marker CD69 increased immediately after primary infection on NK cells and CD8 T cells, while it peaked at about 2 weeks post-infection for CD4 T cells." (PMID 35493734, 2022). "Furthermore, CD40L+ HIV virions might also contribute to the increase the infection rate of CD4 T cells when co-cultured with tonsillar B cells, by promoting the secretion of pro-inflammatory cytokines by B cells, providing a favorable micro-environment for HIV replication." (PMID 36423132, 2022). "At the early phase of the blood stage infection, NK cells, NKT cells, γδ T cells, and T cells were the main producers, followed by a shift of the role to the T cells (CD4+ and CD8+) at the later phase of infection." (PMID 35677654, 2022). "While the coculture of uninfected RPE cells with enriched CD4 T cells from HCMV seropositive donors induces only negligible degradation of the RPE cell monolayer, the HCMV Merlin GFP infection of the RPE cells induces cytolysis." (PMID 36445084, 2022). "Full model included as independent variables age, BMI, years of infection, cART duration, spine BMD, CD4 + nadir count, TT, SHBG, cFT, LH and FSH." (PMID 34460073, 2022). "Multiple mechanisms, involving nAb, CD4 and CD8 T cells acting in a coordinated manner appear to effectively control established infection." (PMID 34931886, 2022). "A decrease in DC infection was observed only when cells were infected with HIV-C, while in DC/CD4+ T-cell co-cultures, productive infection was impeded using both HIV and HIV-C." (PMID 35204813, 2022). "The first possibility is the activation of pro-inflammatory immune responses and activation of CD4+ and CD8+ cells to confine the infection from spreading and ultimately eliminate the infected antigen-presenting cells." (PMID 35242137, 2022). "In this regard, we have previously reported that α-tubulin acetylation is a key Env/CD4-mediated signal for productive HIV-1 fusion and infection." (PMID 35682862, 2022). "Prostratin not only reactivates latent HIV-1 in vitro in a PKC-dependent NF-κB activation manner, but also down-regulates the expressions of HIV-1 receptor CD4 and co-receptor CXCR4, thus avoiding the novo infection of CD4+ cells." (PMID 36615199, 2022). "(2004) demonstrated that S. mansoni warms can induce anergy in CD4+ and CD8+ T cells in the initial acute stages of infection via selective up-regulation of PD-L1 on the surface of Macrophages (Mφ)." (PMID 36148227, 2022). "Following infection of TCM cells, latency is induced by treatment with cART and isolation of CD4 positive cells, which eliminates actively infected cells." (PMID 35255110, 2022). "In contrast, infection with HIV-1* BFP virions containing Vpx was efficient, yielding 20.28% of BFP+CD4+ T cells, the majority of which also showed a strong depletion of GFP–SAMHD1 (top quadrants, middle top)." (PMID 34949807, 2022). "CD11c+T-bet+ B cells generated in these infections are driven by Toll-like receptor (TLR) signals, and by CD40L, IFN-γ, and IL-21 produced by T-bet+CD4+ T cells." (PMID 35064115, 2022). "Among HIV patients, the CD4 cell count drops a few weeks after HIV infection and then increases again in the following months, yet it is less than the level before infection." (PMID 35846073, 2022). "Later during infection, type I IFN activities influence T cells with the induction of cytokine secreting CD4+ T cells and the stimulation of Granzyme B (GzmB) and IFNγ expression by cytotoxic CD8+ T cells." (PMID 36325470, 2022). "Next, we evaluated both CD4+CD69+ as well as CD4+CD69+CD103+ TRM cell populations in the injected and distal flanks at both 6 and 15 weeks post-infection/immunization." (PMID 35419001, 2022).
infection (continued). "Asymptomatic infection resulted in decreased antibody-dependent cellular cytotoxicity (ADCC) and frequency of SARS-CoV-2-specific CD4+ T cells at late convalescence." (PMID 35185909, 2022). "When we compared the SI against spike MPs by paired analysis between Day 1 and Day 28 of infection, we found that every category responded significantly for AIM+ (OX40+CD40L+) CD4+ T cells." (PMID 36248882, 2022). "We demonstrate that within a deterministic framework the interplay of natural CD4 dynamics, constant levels of latent reservoir reactivation, and constant ART efficacy can recapitulate intricate infection dynamics." (PMID 35969641, 2022). "Th17 cells participate in the dissemination of HIV following infection through their expression of mucosal migration receptors (CCR6, α4β7) and HIV co-receptors (CD4, α4β7, CCR5, and CXCR4) through different biological pathways." (PMID 35197986, 2022). "The longevity of CD4+ T‐cell and memory B cell response against the spike protein (S) seems to be stable, while CD8+ T‐cell response lowered by half at 6–8 months after infection." (PMID 35415890, 2022). "(C) Plots show the percentage of TCR transgenic cells (GFP+, Thy1.1+) among live CD4+ cells from constructs Nb-T1, Nb-T2, and Nb-T3 in the MLN of recipient mice at day 9 post infection." (PMID 35950748, 2022). "As expected, sequential infection with these pathogens increased the frequency of Ag-experienced CD4 and CD8 T cells by day 10 after the first infection (IAV), and these frequencies remained elevated 5 d after the last infection (LCMV-Arm, day 25)." (PMID 35878936, 2022). "CCR5+ CD4+ memory T cells have been identified as specific targets of HIV replication and infection." (PMID 35215997, 2022). "Several human studies have described the detection of CD4 + and CD8 + TRMs within lung tissue after infection with IAV49–53." (PMID 34743182, 2022). "Increased IL-1rα and IL10 expression prior to infection can compromise early immune response to HIV and result in reduced CD4:CD8 ratio." (PMID 35165387, 2022). "Surprisingly, an increase in the percentage of CD4+ T cells and a reduction in the percentage of CD8+ T cells in the spleen were found in the KO rats following infection (P<0.05)." (PMID 35584107, 2022). "Peripheral blood CD4 T cells showed a modest increase of activated caspase 1 during acute SIV infection, which peaked on day 14 to a mean level of 5.5% following infection (P = 0.03 compared to day 0)." (PMID 36000842, 2022). "One study found that ~90% of subjects were positive for SARS-CoV-2 memory CD4+ T cells and ~50% were positive for memory CD8+ T cells after 6 months primary infection." (PMID 34975340, 2022). "Our collective data indicate that SARS-CoV-2 spike-specific CD4+ and CD8+ T cells elicited by BNT162b2 vaccination or prior infection remain largely intact against B.1.1.529." (PMID 35042228, 2022). "For example, infected cART-untreated mice remained immunocompetent with stable CD4+CD8+ ratio at 1 and 4 months after infection, resembling features of patients undergoing effective cART." (PMID 35297660, 2022). "We found that Lm ΔactA infection induced recruitment of CD8+ and CD4+ bTRM in aged mice, along with significantly greater numbers of cytokine-expressing CD8+ bTRM compared to uninfected mice." (PMID 35614490, 2022). "Here we characterised the impact of pre-infection plasma cytokines on the markers of HIV disease progression including viral load, CD4:CD8 ratio and CD4 decline." (PMID 35165387, 2022). "In two studies they report on CD4+ and CD8+ TRM dynamics upon human RSV infection and show that CD8+ TRM abundance prior to infection correlates with reduced symptoms and virus replication." (PMID 36003372, 2022). "HIV primarily targets CD4+ T cells expressing CXCR4 and CCR5 co-receptors, which undergo dramatic depletion during the acute phase of infection." (PMID 35911681, 2022).
infection (continued). "Both infection and vaccination similarly led to increased IV-CD45−tetramer+CD4+CD69+CD103− TRM cells." (PMID 36302057, 2022). "In order to clear an infection effectively, patients must possess CD8+ effector T cells that can kill virally infected cells, as well as CD4+ T cells that can enhance the CD8+ and B cell responses." (PMID 35955740, 2022). "SARS-CoV-2-specific CD4+ T cells were detected 1–15 months post infection and the frequency of SARS-CoV-2-specific central memory CD4+ T cells was increased with the time post-symptom onset." (PMID 36146622, 2022). "In line with two recently published reports on children, we detected a stable proportion of SARS-CoV-2-specific CD4+ and CD8+ T cells in both children and adults up to 12 months after infection." (PMID 36437276, 2022). "Overall, we did not detect major alterations in the T/NK cell composition from PBMCs, but at day 4 after infection, we did observe a drop in naïve CD8+ T cells and an increase in central memory CD4+ T cells (PBMC T/NK subpopulation 3 and 1, respectively)." (PMID 35271298, 2022). "Here, CD4+ T cell production of IFN-γ reduces viral titers and provides protection against secondary infections." (PMID 35880171, 2022). "To test this theory, we monitored peripheral blood CD4+ T cells and plasma viral load throughout SIV-infection." (PMID 36561749, 2022). "Resting CD4 cells are known to be early HIV targets in vivo, in contrast to their relative resistance to infection in vitro." (PMID 34465136, 2022). "There as a significant correlation (using Spearman Rank Correlations) between the maximum post-infection IFN-γ responses to the CD4+CD8 pool and post-infection IFN-γ responses to the S, N and N+M pools (comparisons excluded the M pool alone group)." (PMID 35390102, 2022). "Adequate CD4 and CD8 T cell activation to proliferation, clonal expansion and effector function is crucial for efficient clearance of infection by pathogens." (PMID 35359994, 2022). "The infection of SARS-CoV-2 can lead to lymphocytopenia and imbalance of lymphocyte subsets, such as decreased CD4+ T cells, CD8+ T cells, B cells, and NK cells." (PMID 37359706, 2022). "We present evidence regarding a novel role of QS as a multifunctional mechanism coordinating CD4+ and CD8+ T cell behavior during steady state and in response to infection, inflammatory diseases, and cancer." (PMID 35954285, 2022). "The results showed that PRRSV infection induced the dominant activation of CD4 T cells in mediastinal lymph nodes and CD8 T cells in the spleen at 14 days post-infection, in terms of CD69 expression." (PMID 35746813, 2022). "U87-MG CD4/CXCR4 cells expressing wild-type MX2 or the S28D, T151D, T343D, or S28D/T151D mutants were challenged with these stocks, and infection was measured at 48 h." (PMID 35880880, 2022). "Our data provide information on the co-expression of CD4 and HIV-1 co-receptors on HSPC subsets, which is in the range of 0.55% to 4.52% and parallels the rates of in vitro infection in our and others’ studies." (PMID 36230931, 2022). "We report here that SARS-CoV-2 spike-specific CD4+ and CD8+ T cells induced by prior infection or BNT162b2 vaccination provide extensive immune coverage against B.1.1.529." (PMID 35042228, 2022). "It is somewhat unlikely that the infection of the CAR T cells by SIV and subsequent cell death is a major contributor to low persistence of our CD4-MBL CAR/CXCR5 T cells." (PMID 36582226, 2022). "During infection, killing of HIV-infected CD4+ T lymphocytes by CTLs is a major mechanism of viral suppression." (PMID 35062339, 2022). "Therefore, the presence of elevated levels of TNF-α and the increase of lymphocytes T CD4+ in patients under DMARDs treatment could suggest a relation between the poor response to treatment and the infection by protozoa, even though more robust studies are required to delve into this aspect." (PMID 35492365, 2022).